MROH3P (maestro heat like repeat family member 3, pseudogene)
Synonyms: formerly C1orf81
Gene: Transcribed unitary pseudogene on chromosome 1 (200,917,460 to 200,966,536, forward strand). Ensembl gene ENSG00000233217.
Diseases named in the same sentence as MROH3P in open-access papers:
MROH3P is named in the same sentence as 2 diseases in open-access papers, as found by Europe PMC text mining. Sharing a sentence is not in itself a finding about the gene and the disease.
MROH3P shares sentences with these, for which no sentence is quoted: Crohn disease (1 paper); Parkinson disease (1).